TP53INP2 (tumor protein p53 inducible nuclear protein 2)
Description:
Dual regulator of transcription and autophagy. Positively regulates autophagy and is required for autophagosome formation and processing. May act as a scaffold protein that recruits MAP1LC3A, GABARAP and GABARAPL2 and brings them to the autophagosome membrane by interacting with VMP1 where, in cooperation with the BECN1-PI3-kinase class III complex, they trigger autophagosome development. Acts as a transcriptional activator of THRA.
Synonyms: C20orf110; DOR; PINH; FLJ21759; FLJ23500; DKFZp434B2411; DKFZp434O0827; dJ1181N3.1
Tractability: No criterion of Open Targets' tractability assessment is met for any kind of drug.
Gene: Protein-coding gene on chromosome 20 (34,701,662 to 34,713,439, forward strand). Ensembl gene ENSG00000078804.
Subcellular location: Cytoplasm, cytosol; Nucleus; Nucleus, PML body; Cytoplasmic vesicle, autophagosome
Gene Ontology:
Molecular function: protein binding; ubiquitin binding
Biological process: autophagosome assembly; positive regulation of DNA-templated transcription
Cellular component: autophagosome; cytosol; nucleus; PML body
Genetic constraint (gnomAD): Loss-of-function variants: 12 observed, 13.97 expected, observed/expected ratio (o/e) 0.86, 90% interval 0.55 to 1.39. The upper end of that interval is the gene's LOEUF score, 1.39, which puts it in group 5 of 6, group 1 being the genes least tolerant of losing a copy. Missense variants: 342 observed, 281.5 expected, observed/expected ratio (o/e) 1.21, 90% interval 1.11 to 1.33. Synonymous variants: 145 observed, 118.94 expected, observed/expected ratio (o/e) 1.22, 90% interval 1.06 to 1.4.
Homologues: Orthologues: chimpanzee TP53INP2 (98% identical), macaque TP53INP2 (96% identical), dog TP53INP2 (91% identical), pig TP53INP2 (90% identical), guinea pig TP53INP2 (90% identical), rat Tp53inp2 (86% identical), mouse Trp53inp2 (86% identical), tropical clawed frog tp53inp2 (48% identical), zebrafish tp53inp2 (22% identical). Paralogues in human: TP53INP1 (31% identical).
Diseases named in the same sentence as TP53INP2 in open-access papers:
TP53INP2 is named in the same sentence as 40 diseases in open-access papers, as found by Europe PMC text mining. Sharing a sentence is not in itself a finding about the gene and the disease. The quoted sentences say what the papers report.
Diabetes (6 papers, 2012 to 2026). "Finally, overactivation of autophagy obtained through TP53INP2/Dor overexpression was shown to exacerbate the loss of muscle mass observed in experimental diabetes, confirming that both direct inhibition and stimulation of autophagy are detrimental in wasting conditions." (PMID 30833900, 2019). "TP53INP2 expression was markedly reduced in muscle from individuals with type 2 diabetes and in rodent diabetes models." (PMID 26426971, 2015). "The nuclear cofactor DOR (Diabetes- and Obesity-Regulated gene, also known as Tp53inp2 or C20orf110), is a key regulator of autophagy." (PMID 22470510, 2012). "Furthermore, TP53INP2, also known as DOR (Diabetes And Obesity-Regulated Gene), has been linked to obesity and diabetes, suggesting a novel biological pathway for the known association between obesity and breast cancer risk." (PMID 28957356, 2017). "Interestingly, Tp53inp2 has also been named the DOR (Diabetes and Obesity Related) gene, as its expression is substantially reduced in skeletal muscle of obese diabetic fa/fa Zucker rats." (PMID 26426971, 2015). "The deacetylated LC3 interacts with Diabetes and Obesity Regulator (DOR; also known as TP53INP2) and translocates to the cytoplasm, where it interacts with ATG7 to promote autophagy." (PMID 41513612, 2026).
bladder cancer (5 papers, 2021 to 2025). "In bladder cancer, TP53INP2 influences cell migration, invasion, and epithelial-mesenchymal transition (EMT) by regulating the GSK-3β/β-catenin/Snail1 pathway." (PMID 40755754, 2025). "Apart from being involved in autophagy, TP53INP2 can modulate epithelial-to-mesenchymal transition via the GSK-3β/β-Catenin/Snail1 pathway in bladder cancer cells." (PMID 36675134, 2023). "In bladder cancer, TP53INP2 is a modulator in cell migration, invasion, and EMT by going with the GSK-3beta/beta-catenin/Snail1 pathway." (PMID 35615533, 2022). "In bladder cancer, TP53INP2 is upregulated and knockdown of TP53INP2 inhibits the invasion, migration as well as epithelial-to-mesenchymal transition." (PMID 33897760, 2021). "Finally, intersecting these key genes with risk-consistent genes yielded eight immune-related genes that were negatively associated with bladder cancer risk: LIMS2, TP53INP2, IRAK3, STX2, CYP27A1, IL11RA, KCNMB1, and PDLIM7." (PMID 40755754, 2025). "Mendelian randomization (MR) analysis revealed a negative causal association between TP53INP2 expression levels and bladder cancer risk." (PMID 40755754, 2025). "However, TP53INP2 acts as an oncogene in bladder cancer evidenced by its promotion of migration and invasion in bladder cancer cells." (PMID 33897760, 2021). "Given that TAMs are the most abundant immune cell population in the tumor microenvironment, and that autophagy regulates their polarization toward the M2 phenotype, this study proposes that downregulation of TP53INP2 may modulate bladder cancer development by influencing macrophage polarization." (PMID 40755754, 2025). "Although no clinical interventions targeting TP53INP2 have yet been established, its unique mechanism of regulating bladder cancer progression via the autophagy–macrophage axis makes it a potential target for immunotherapy." (PMID 40755754, 2025).
Obesity (5 papers, 2015 to 2024). Accumulation of substantial excess body fat. "Also, known as DOR (diabetes- and obesity-regulated gene), TP53INP2 has been linked to obesity and diabetes." (PMID 28957356, 2017). "TP53INP2 is involved in the occurrence and development of various diseases, such as cancer, myocardial injury, and obesity." (PMID 38652010, 2024). "TP53INP2, a nuclear protein, is highly expressed in actively metabolizing tissues and is involved in cellular processes including obesity, transcription, autophagy, and apoptosis." (PMID 35954230, 2022). "The identification of TP53INP2/DOR as breast cancer-related gene could provide novel insight on the mechanism for obesity-breast cancer relationship." (PMID 28957356, 2017). "Finally, it is interesting to note that the TP53INP1 paralog TP53INP2 (also known as DOR for diabetes and obesity related) is also involved in MS through its implication in autophagy." (PMID 25828351, 2015).
breast carcinoma (4 papers, 2017 to 2024). "This inverse correlation between TP53INP2 expression and cancer proliferation is consistent with our finding that TP53INP2 expression inversely correlated with breast cancer risk." (PMID 28957356, 2017). "In this gene-level expression-based genome-wide association analysis of five breast cancer GWAS datasets composed of individuals of diverse ancestry, we identified TP53INP2 (20q11.22) as gene with genetically-determined expression that is associated with ER-negative breast cancer." (PMID 28957356, 2017). "Future studies need to determine whether the TP53INP2 gene is a true susceptibility gene for breast cancer and what are the underlying mechanisms for its association with ER-negative breast cancer." (PMID 28957356, 2017). "TP53INP2-related SNPs and their association with breast cancer risk." (PMID 28957356, 2017). "A recent study showed that high levels of TP53INP2 are correlated with TRAIL-triggered cell death in breast cancer." (PMID 38909249, 2024). "For overall breast cancer risk, there was no gene with a P-value that deviated from the null distribution, but for ER-negative breast cancer risk analysis, there were several genes with P-values smaller than expected, including TP53INP2, HP, and DHODH." (PMID 28957356, 2017).
melanoma (4 papers, 2015 to 2021). A malignant, usually aggressive tumor composed of atypical, neoplastic melanocytes. "Overexpression of miR‐638 is reported in metastatic lesions compared with primary melanomas; it downregulates the TP53INP2 oncosuppressor and thereby protects melanoma cells from apoptosis and autophagy." (PMID 30499222, 2019). "Overexpression of TP53INP2 cDNA in melanoma cells resulted in significant attenuation of their proliferative and invasive potential which was rescued upon miR-638 co-transfection." (PMID 25650662, 2015). "Knockdown of miR-638 in melanoma cells increased expression of TP53INP2 and induced significant levels of autophagy." (PMID 25650662, 2015). "Overexpression of TP53INP2 severely attenuated proliferative and invasive capacity of melanoma cells which was reversed by miR-638." (PMID 25650662, 2015). "The expression of TP53INP2 was markedly reduced in most of the melanoma cell lines as compared to benign cells." (PMID 25650662, 2015). "Moreover, the mRNA and protein levels of TP53INP2 in melanoma cells were significantly suppressed upon transfection of miR-638." (PMID 25650662, 2015). "Indeed, overexpression of TP53INP2 cDNA strongly attenuated growth and invasion of melanoma cells." (PMID 25650662, 2015).
colon cancer (3 papers, 2020 to 2023). "Additionally, it is said that TP53INP2 overexpression induces the activation of colon cancer cell autophagy via the HEDGEHOG signaling pathway." (PMID 36675134, 2023).
leukemia (3 papers, 2023 to 2024). A malignant (clonal) hematologic disorder, involving hematopoietic stem cells and characterized by the presence of primitive or atypical myeloid or lymphoid cells in the bone marrow and the blood. "Followingly, we looked into the reason that TP53INP2 is largely located in the cytoplasm of NPM1-mutated leukemia cells." (PMID 36675134, 2023). "The results showed that TP53INP2 was dramatically upregulated in NPM1-mutated leukemia patients (n = 21) compared with NPM1-unmutated leukemia patients (n = 18)." (PMID 36675134, 2023). "Here, we used bioinformatics analysis to screen out the autophagy-associated dysregulated gene TP53INP2 in NPM1-mutated leukemia." (PMID 36675134, 2023). "To clarify the role of TP53INP2 in the autophagy process of NPM1-mutated leukemia cells, we first silenced TP53INP2 to observe the changes in autophagic level." (PMID 36675134, 2023). "Next, we explored the molecular mechanism underlying the high expression of TP53INP2 in NPM1-mutated leukemia cells." (PMID 36675134, 2023). "Of course, further work is necessitated to clarify the role of TP53INP2-mediated autophagy in mouse knock-in models that mimic human NPM1-mutated leukemia." (PMID 36675134, 2023). "Therefore, a deeper exploration of other biological functions of TP53INP2 contributes to revealing its distinct role in NPM1-mutated leukemia." (PMID 36675134, 2023). "Next, we attempted to explore the biological function of TP53INP2 in NPM1-mutated leukemia cells." (PMID 36675134, 2023). "Indeed, RNA-seq data from another study also indicated the upregulation of TP53INP2 in NPM1-mutated leukemia cells." (PMID 36675134, 2023). "Therefore, further studies are needed to investigate whether TP53INP2 regulates other autophagy-related components to engage in the autophagy process in NPM1-mutated leukemia." (PMID 36675134, 2023). "In the current study, we first utilized bioinformatics analysis to ascertain the dysregulated genes associated with autophagy in NPM1-mutated leukemia and obtained three genes including TUSC1, NKX2-3, and TP53INP2." (PMID 36675134, 2023). "Collectively, these results indicate that TP53INP2-enhanced autophagy is essential for the survival of NPM1-positive leukemia cells." (PMID 36675134, 2023). "The findings demonstrate that TP53INP2 is delocalized into the cytoplasm of leukemia cells by interacting with NPM1-mA." (PMID 36675134, 2023). "In the end, we assessed the role of TP53INP2-mediated autophagy in maintaining the survival of leukemia cells." (PMID 36675134, 2023). "To further determine the TP53INP2 expression in NPM1-mutated leukemia, we acquired the RNA-seq data of TP53INP2 in a group of leukemia-lymphoma cell lines in the CCLE database." (PMID 36675134, 2023). "Then, the expression of TP53INP2 transcripts in leukemia blasts derived from AML patients was detected." (PMID 36675134, 2023). "Taken together, our study indicates that TP53INP2 plays an oncogenic role in maintaining the high autophagy activity of NPM1-mutated AML and provides further insight into autophagy-targeted therapy of this leukemia subtype." (PMID 36675134, 2023). "Functionally, cytoplasmic TP53INP2 enhanced autophagy activity by promoting the interaction of microtubule-associated protein 1 light chain 3 (LC3) - autophagy-related 7 (ATG7) and further facilitated the survival of leukemia cells." (PMID 36675134, 2023). "Next, we explored the molecular mechanism by which TP53INP2 activated autophagy in leukemia." (PMID 36675134, 2023). "The results showed that there is higher TP53INP2 expression in OCI-AML3 cells with NPM1 mutation type A(NPM1-mA) compared to other leukemia cell lines without NPM1-mA." (PMID 36675134, 2023). "In leukemia cells with nucleophosmin 1 (NPM1) mutations, FTO reduces m6A levels and enhances autophagy by upregulating the expression of TP53INP2 and promoting the LC3-ATG7 interaction, which is critical for the survival of NPM1-positive leukemia cells." (PMID 39468015, 2024).
leukemia (continued). "Finally, we explored whether TP53INP2-enhanced autophagy is required for leukemia cell survival." (PMID 36675134, 2023). "However, the role of TP53INP2 in leukemia, especially in NPM1-mutated leukemia, has been unknown." (PMID 36675134, 2023). "More importantly, cytoplasmic TP53INP2 could promote the interaction of LC3-ATG7 to enhance autophagy activity and further facilitate leukemia cell proliferation." (PMID 36675134, 2023). "Importantly, cytoplasmic TP53INP2 enhanced autophagy activity by promoting the interaction of LC3-ATG7, thereby maintaining leukemia cell survival." (PMID 36675134, 2023). "In this work, we also observed that cytoplasmic TP53INP2 was more abundant in leukemia cells with NPM1-mA than those without NPM1-mA." (PMID 36675134, 2023).
liposarcoma (3 papers, 2022 to 2024). A usually painless malignant tumor that arises from adipose tissue. "Overexpression of TP53INP2 in human liposarcoma cells would lead to an increasement in LC3 II/LC3 I ratio as well as a decreasement in p62 expression." (PMID 35615533, 2022). "Expression of TP53INP2 might be deemed as the biomarker in predicting human liposarcoma malignancies." (PMID 35615533, 2022).
acute myeloid leukemia (2 papers, 2024). Acute myeloid leukemia (AML) is a group of neoplasms arising from precursor cells committed to the myeloid cell-line differentiation. "In acute myeloid leukemia (AML), TP53INP2 is upregulated by FTO-mediated modification of m6A, which enhances autophagy activity by promoting the interaction of LC3 and ATG7, ultimately promoting leukemia cell survival." (PMID 38576024, 2024).
gastric cancer (2 papers, 2023). A primary or metastatic malignant neoplasm involving the stomach. "In a recent study, inactivation of ZSCAN18 by DNA methylation drives the proliferation via attenuating TP53INP2-mediated autophagy in gastric cancer." (PMID 37223020, 2023). "In a recent research of gastric cancer, methylation-silenced ZSCAN18 induces the proliferation via weakening TP53INP2-mediated autophagy." (PMID 37223020, 2023).
head and neck squamous cell carcinoma (2 papers, 2021 to 2024). A squamous cell carcinoma that arises from any of the following anatomic sites: lip and oral cavity, nasal cavity, paranasal sinuses, pharynx, larynx, and salivary glands. "TP53INP2 plays an important role in regulating gene transcription and starvation-induced autophagy, however, its function in head and neck squamous cell carcinoma (HNSCC) remains unclear." (PMID 33897760, 2021).
adenoma (1 paper, 2016). A neoplasm arising from the epithelium. "The commonly repressed genes in these two adenoma samples include BCL2L11, TP53INP2, HIST1H1C, TRPM6, MIR22HG, and MIR5047." (PMID 27100181, 2016).
Alzheimer disease (1 paper, 2015). A progressive, neurodegenerative disease characterized by loss of function and death of nerve cells in several areas of the brain leading to loss of cognitive function such as memory and language. "In this work, we focused on knowledge cliffs next to some of the most-established interactions such as BACE1-APP and found four “potential new candidates”, namely TP53INP2, RTN4, F2RL3, and FBXO2, presumably new targets for Alzheimer’s disease as guided by the knowledge cliff concept." (PMID 26346705, 2015).
autism (1 paper, 2015). Persistent deficits in social interaction and communication and interaction as well as a markedly restricted repertoire of activity and interest as well as repetitive patterns of behavior. "Some have been associated with neurodevelopmental disorders: schizophrenia (DIXDC1, ARVCF, MAGI2, ZIC2), ADHD (attention deficit/hyperactivity disorder) (TCERG1L), movement disorders (NOL3, TP53INP2), Huntington’s disease (H2AFY2, AGPAT1), Parkinson’s disease (LMX1B), and autism (PLXNA4, WNT2)." (PMID 25748564, 2015).
cardiac hypertrophy (1 paper, 2023).
colorectal cancer (1 paper, 2025). A primary or metastatic malignant neoplasm that affects the colon or rectum. "Previous studies have shown that TP53INP2 expression is significantly decreased in colorectal cancer tissues, and its silencing promotes tumor cell proliferation." (PMID 40755754, 2025).
estrogen-receptor negative breast cancer (1 paper, 2017). "There are 6 single nucleotide polymorphisms (SNPs) included in the prediction of TP53INP2 expression and five of them were associated with estrogen-receptor negative breast cancer, although none of the SNP-level associations reached genome-wide significance." (PMID 28957356, 2017).
oral squamous cell carcinoma (1 paper, 2021). "Additionally, SOX21-AS1 has been reported to be a tumor suppressor gene in oral squamous cell carcinoma and it was up-regulated in TP53INP2-high patients." (PMID 33897760, 2021).
osteoporosis (1 paper, 2023). A condition of reduced bone mass, with decreased cortical thickness and a decrease in the number and size of the trabeculae of cancellous bone (but normal chemical composition), resulting in increased fracture incidence. "In osteoporosis, oxidative stress induces TP53INP2 downregulation and suppresses osteogenic differentiation of BMSCs during osteoporosis through the autophagy degradation pathway." (PMID 37925525, 2023).
ovarian carcinoma (1 paper, 2023). A malignant neoplasm originating from the surface ovarian epithelium. "hnRNPA2 regulates alternative mRNA splicing of TP53INP2 to control invasive cell migration in ovarian cancer." (PMID 37639158, 2023).
pancreatic cancer (1 paper, 2023). "In keeping with our findings, TP53INP2 is reported to induce autophagy activation to promote pancreatic cancer progression." (PMID 36675134, 2023).
renal cell carcinoma (1 paper, 2022). "Collectively, our results suggested that the TP53INP2 inhibited renal cell carcinoma in a way of regulating the caspase-8/TRAF6 apoptotic signaling pathway." (PMID 35615533, 2022).